DYNLT4 (dynein light chain Tctex-type 4)
Synonyms: TCTEX1D4
Tractability: No criterion of Open Targets' tractability assessment is met for any kind of drug.
Gene: Protein-coding gene on chromosome 1 (44,805,888 to 44,807,417, reverse strand). Ensembl gene ENSG00000188396.
Subcellular location: Cell projection, cilium, flagellum; Cytoplasmic vesicle, secretory vesicle, acrosome; Cytoplasm, cytoskeleton, cilium axoneme; Cytoplasm; Nucleus; Cytoplasm, cytoskeleton, microtubule organizing center
Subcellular location (Human Protein Atlas): Vesicles
Gene Ontology:
Molecular function: protein binding; protein phosphatase 1 binding; dynein intermediate chain binding
Biological process: microtubule-based movement
Cellular component: acrosomal vesicle; axoneme; microtubule organizing center; sperm flagellum; cytoplasm; cytoplasmic dynein complex; nucleus; motile cilium
Genetic constraint (gnomAD): Loss-of-function variants: 7 observed, 4.32 expected, observed/expected ratio (o/e) 1.62, 90% interval 0.84 to 1.94. That is too few expected variants to judge how well the gene tolerates losing a copy. Missense variants: 346 observed, 256.39 expected, observed/expected ratio (o/e) 1.35, 90% interval 1.24 to 1.48. Synonymous variants: 181 observed, 119.98 expected, observed/expected ratio (o/e) 1.51, 90% interval 1.34 to 1.71.
Homologues: Orthologues: chimpanzee DYNLT4 (99% identical), macaque DYNLT4 (93% identical), rabbit DYNLT4 (80% identical), pig DYNLT4 (79% identical), dog DYNLT4 (75% identical), rat Dynlt4 (71% identical), guinea pig DYNLT4 (70% identical), mouse Dynlt4 (70% identical), tropical clawed frog dynlt4 (39% identical). Paralogues in human: DYNLT2 (20% identical), DYNLT2B (19% identical), DYNLT5 (19% identical), DYNLT1 (8% identical), DYNLT3 (8% identical).
Diseases named in the same sentence as DYNLT4 in open-access papers:
DYNLT4 is named in the same sentence as 2 diseases in open-access papers, as found by Europe PMC text mining. Sharing a sentence is not in itself a finding about the gene and the disease.
DYNLT4 shares sentences with these, for which no sentence is quoted: lung carcinoma (1 paper); tumor (1).